IL25 (interleukin 25)
Diseases named in the same sentence as IL25 in open-access papers (continued):
Sharing a sentence is not in itself a finding about the gene and the disease.
tumor (continued). "Studies in the past decade have begun to uncover the important roles of IL-25 and IL-33 in shaping the CRC tumour immune microenvironment, where they may promote or inhibit tumorigenesis depending on the specific CRC subtype." (PMID 36263033, 2022). "Furthermore, both IL-25 and IL-33 modulate pathways previously known to contribute to CRC tumorigenesis, including angiogenesis, tumour stemness, invasion and metastasis." (PMID 36263033, 2022). "Importantly, depletion of DCLK1+ tuft cells reduced tumour burden in models of CRC both in vitro and in vivo, indicating that these IL-25-expressing tuft cells can support intestinal tumorigenesis." (PMID 36263033, 2022). "Both IL-25 and IL-33 have been shown to promote CRC tumour cell stemness." (PMID 36263033, 2022). "Analysis of IL-25 expression in healthy colons and CRC showed comparable levels in one report, while a more recent study found IL-25 expression to be elevated in human CRC tumours compared to the adjacent normal gut." (PMID 36263033, 2022). "Interestingly, in the primary tumor, CD206+ macrophages were significantly reduced after anti-IL-25 antibody treatment, which were reported to promote tumor growth and metastasis." (PMID 27909985, 2017). "We found that only tumor-infiltrating CD4+ T cells, but not CD8+ T, macrophages or tumor cells express IL-17RB – the receptor for IL-25." (PMID 27909985, 2017). "In this study, we noticed that anti-IL-25 treatment only reduced the IL-4-producing Th2 cells in the tumor microenvironment, but did not affect the expression of IL-5 and IL-13." (PMID 27909985, 2017). "An IL-25 neutralization antibody, while not affecting primary tumor growth, substantially reduced lung metastasis." (PMID 27909985, 2017). "On the other hand, for those 3T3 fibroblasts treated with Q2-3, the cells co-cultured with 4T1 metastatic tumour cells expressed a lower level of IL-25, compared with fibroblasts that were not co-cultured with any tumour cells." (PMID 27089063, 2016). "Through the study of HCC cell lines (Huh7, PLC/PRF/5, HCC cells T1115 and T1224) and models, researchers found non-cancer cell stem cells (non-CSCs) could secrete IL-25 into the tumor microenvironment, and secreted IL-25 interacts with IL-17RB on CSCs." (PMID 37005677, 2023). "Thus, IL-25 predominantly regulates ILC2s, rather than adaptive Th2 lymphocytes correlating to a tumor-permissive niche." (PMID 35658010, 2022). "Experimental IL-25-signaling blockade (using the D9.2 clone which also blocks human IL-25R) inhibited ILC2 production of IL-4 and IL-13, limiting the suppressive capacities of MDSCs, thereby permitting the liberation of anti-tumor T cell and IFNγ-mediated immunity and reduced CRC." (PMID 35658010, 2022). "However, as described, IL-33 play the major role in ILC2s activation since IL-25 activate only iILC2s and TLSP may trigger TSLP receptors expressed by tumor cells in an autocrine manner and independently from a type 2 inflammation." (PMID 33233582, 2020). "However, our studies showed that tumor macrophages in the MMTV-PyMT tumor model did not express IL-17RB and thus cannot directly respond to IL-25, similar to the alternatively activated macrophages as reported." (PMID 27909985, 2017). "These mRNA and IHC data also suggest that tumor cells are not a major source of IL-25." (PMID 27909985, 2017). "Unlike the previous in vitro studies, we noticed that the tumor cells in the MMTV-PyMT tumor model did not express IL-17RB – the receptor for IL-25, and thus could not respond directly to IL-25 treatment." (PMID 27909985, 2017). "Interestingly, under some circumstances, IL-17E (IL-25) produced by nonmalignant mammary epithelial cells also displays antitumor function by targeting adjacent tumor cells, which express high levels of IL-25R and inducing apoptosis." (PMID 26783383, 2015).
tumor (continued). "However, some studies reported this expression just on tumor-infiltrating CD4+ T-cells, and infrequently on tumor cells, or could not find IL-25 in the T-cells isolated from the tumoral and adjacent tissues of the patients with different molecular subtypes." (PMID 37835465, 2023). "Therefore, anti-IL-25 did not affect the survival of tumor-bearing mice in our hands." (PMID 27909985, 2017). "Although our study has indicated that GC tumor cells might express IL-25R in situ, and that both T cells and Mφs expressed IL-25R in GC tissue; we did not observe cytotoxic activity in vitro using recombinant human IL-25 in GC cell lines (data not shown)." (PMID 26840565, 2016). "Critically, rIL-25 treatment increased tumour burden in ILC2-replete but not ILC2-deplete Apc1322T/+ mice, indicating an essential role for ILC2 in driving IL-25-mediated CRC tumorigenesis." (PMID 36263033, 2022). "Despite anti-IL-25 treatment significantly reduced lung metastasis in the MMTV-PyMT tumor model, it did not affect the growth of primary tumor and the survival of tumor mice." (PMID 27909985, 2017). "Although the development of primary tumor and the survival rate of MMTV-PyMT mice were not altered, anti-IL-25 antibody treatment reduced lung metastasis by >60%, as determined by the numbers of tumor nodes." (PMID 27909985, 2017).
cancer (40 papers, 2014 to 2025). A tumor composed of atypical neoplastic, often pleomorphic cells that invade other tissues. "Conversely, 28 pathways in the KO_IL-25/IL-33 transcriptomes were associated with cytokine–cytokine receptor interaction, pathway in cancer, glutathione metabolism, purine, and pyrimidine as well as Ras/Rap1 signaling." (PMID 37337050, 2023). "During AOM and DSS challenge, genetic deletion of IL25 had retarded the development of colitis-associated cancer." (PMID 35359953, 2022). "These may underlie the differential roles of IL-33 and IL-25 in different cancer types depending on the tissue site." (PMID 37455828, 2023). "Secukinumab IL-25, a subtype of IL-17, has been linked to a perplexing role in cancer." (PMID 35054524, 2022). "In the future, IL25 inhibition will be a new clinical strategy for colitis-associated cancer." (PMID 35359953, 2022). "Eosinophil-derived IL-17 may be implicated in antitumor activity, since IL-17E (IL-25) exerts antitumor activity against many types of cancerous cell lines, at least in xenograft models using human cancer cells in mice." (PMID 25426119, 2014). "We further explore cancer-type-specific signaling pathways regulating tuft cell differentiation and function, such as IL-25, acetylcholine, and taste receptor-related pathways." (PMID 42211052, 2025). "IL-25 and IL-33 are well-established type 2 immune-related cytokines with recently discovered roles in cancer immunity." (PMID 37455828, 2023). "The type 2 immunity-related cytokines IL-25 and IL-33 with recently discovered roles in cancer are also explored in light of their potential as novel immunotherapeutic targets." (PMID 37455828, 2023). "In investigations related to liver cancer, IL-25 was found to maintain the self-renewal of human cancer stem cells via the activation of STAT3 and NF-κB." (PMID 37005677, 2023). "Although IL-25 inhibition therapy has shown promising results in cancer treatment, it, like IL-17, has a double-edged effect in cancer patients." (PMID 35054524, 2022). "Our data demonstrated that IL25 was especially expressed in colorectal CSCs and is essential for maintaining cancer stemness." (PMID 35359953, 2022). "Here, we showed that intestinal IL-25-activated ILC2s created an innate cancer-permissive microenvironment." (PMID 35658010, 2022). "It has been suggested that lung group 2 innate lymphoid cells (ILC2), which produce IL-5 or IL-13 in response to IL-25 and IL-33, suppress the lung metastasis of cancer cells." (PMID 34170380, 2022). "Recent investigations have reported that IL‐25 targeting in IL‐25R‐expressing cancer results in positive clinical responses." (PMID 34128588, 2021). "Regarding using IL‐25 as a biomarker, since immune responses are relatively different at each stage of diseases, this study proposes that future investigations should be more focused on the dysregulation of IL‐25 at different stages of cancer." (PMID 34128588, 2021). "It is hoped that studies regarding newly identified cytokines such as IL‐25 involvement in cancer would expand our knowledge regarding cancer." (PMID 34128588, 2021). "Since IL‐17RB is a common receptor for IL‐25 and IL‐17B, it is found that IL‐17B can induce pro‐neoplastic properties in cancer cells." (PMID 34128588, 2021). "IL‐25 holds great promise for developing effective and novel cancer treatment with a broad therapeutic approach." (PMID 34128588, 2021). "The expression of IL‐25 and its receptor have been dysregulated in various cancers compared with normal tissues." (PMID 34128588, 2021). "Concerning the IL‐17 family, especially IL‐25, it has been shown that this cytokine has been dysregulated during cancer." (PMID 34128588, 2021). "Most studies concerning IL‐25 involvement in cancer have been studied in vitro and cancer cell lines." (PMID 34128588, 2021).
cancer (continued). "Further assessments of interleukins in cancer therapy are largely occurring at the preclinical level, with promising findings for targets such as IL-25 as previously discussed." (PMID 32082375, 2019). "As an inflammatory factor, IL‐25 has been studied in variouscancers, but it is rarely reported in cancer chemotherapy resistance." (PMID 31044552, 2019). "This is the first study of its kind to specifically examine the influence of IL-25 in a long-term inflammation-induced cancer model." (PMID 27165713, 2016). "The secretion of IL-25 from treated human or mouse fibroblasts is enhanced in vitro, and this activity confers a strong suppressive effect on growth activity of test carcinoma cells." (PMID 27089063, 2016). "IL-25 can also induce JAK/STAT3 signaling pathway to promote self-renewal of cancer cells." (PMID 38818476, 2024). "The presence of different subsets of ILC2 cells in IL-33-expressing and IL-25-expressing cancers could explain the discrepancies in their observed functions." (PMID 37781372, 2023). "The IL-17 family of cytokines is composed of six members named IL-17A (commonly known as IL-17), IL-17B, IL-17C, IL-17D, IL-17E (also known as IL-25), and IL-17F with different sequence homology and functions that are important players in host defense responses, inflammation, and cancer development." (PMID 38068860, 2023). "Therefore, translational studies are required to determine the biological function of IL-25 in cancer development." (PMID 37005677, 2023). "Meanwhile, IL-25 also plays an important role in several human cancers." (PMID 36119529, 2022). "Thus, the roles of innate epithelium-derived cytokines IL-25 and IL-33, and ILC2s in cancer cannot be generalized." (PMID 35658010, 2022). "Read in conjunction, IL25 may play a curial role in chemotherapy resistance of CRC derived by tuft or cancer stem cells." (PMID 35359953, 2022). "Moreover, deletion of IL25 decreased the frequency of cancer organoid formation, which was reversed by IL25." (PMID 35359953, 2022). "The gene signatures of cancer stem cells were positively correlated with IL25 expression." (PMID 35359953, 2022). "Until recently, the role of IL-25 in cancer has been largely speculative and few studies to date investigated the downstream immune mechanisms of IL-25 in CRC." (PMID 36263033, 2022). "Whether cancers at other sites of the body may recruit these pro-tumorigenic IL-25-responsive intestinal ILC2s potentially to sustain MDSCs remains to be explored." (PMID 35658010, 2022). "It is hoped that using combination therapies with an IL‐25‐based therapeutic approach might be promising in cancer treatment." (PMID 34128588, 2021). "This included decreased anti-inflammatory factors such as IL-4, IL-13, M-CSF and CXCL12 and antitumor factors SCF, FLT-3L and IL-25 that could contribute to cancer progression and metastasis." (PMID 34575976, 2021). "Also, it is important to determine the sensitivity, specificity, and accuracy of IL‐25 levels in various cancers." (PMID 34128588, 2021). "Moreover, since IL‐17B and IL‐25 have a common receptor called IL‐17RB, it is also required to define which ligand is involved in the cancer progression." (PMID 34128588, 2021). "Since tyrosine kinases are involved in IL‐25R signaling, using tyrosine kinase inhibitors (TKIs) in cancers in which IL‐25 promotes its progression might provide a new approach in cancer therapies." (PMID 34128588, 2021). "This study is focused on the role of IL‐25 in cancer development." (PMID 34128588, 2021). "However, there are pieces of evidence emphasizing the involvement of IL‐25 in cancer development and progression." (PMID 34128588, 2021). "Simultaneously, IL-25 also plays an important role in several human cancers." (PMID 31296243, 2019). "IL‐25 may play different roles in different cancers, either as a cancer suppressor or as a cancer promoter." (PMID 31044552, 2019).
cancer (continued). "Whether IL-25 is involved in the progression from inflammation to cancer is still largely unexplored." (PMID 27165713, 2016). "Similarly, studies have found that the mRNA expression level of interleukins 25 (IL-25) in PBMCs of malignant and benign breast patients was significantly lower than that of non-cancer individuals (P < 0.05), and the decrease of IL-25 was also related to the grading and staging of breast cancer." (PMID 41450733, 2025). "Similarly, type 2 immunity-related cytokines IL-25 and IL-33 with recently characterised roles in cancer may either promote or suppress tumorigenesis in a context-dependent manner." (PMID 37455828, 2023). "Consequently, we examine how targeting the inhibition of IL-25, IL-33 and type 2 intestinal immunity, to release the brakes on type 1 anti-cancer immunity, may be beneficial in certain CRC subtypes, but detrimental in others." (PMID 36263033, 2022). "Collectively, it is hoped that IL-25 could be a promising cancer treatment target." (PMID 35885460, 2022). "Moreover, IL‐25‐based therapeutic approaches have shown promising results in cancer inhibition." (PMID 34128588, 2021). "Therefore, we have decided to shed more light on the role of IL‐25 in cancer." (PMID 34128588, 2021). "Therefore, it has been indicated that IL‐25 might play a multifarious role in cancer progression or regression." (PMID 34128588, 2021). "Since IL‐25 is the distinguished member of this family, it is suggested that this cytokine might exhibit different functions compared with other members in various biological and pathological conditions, especially in cancer." (PMID 34128588, 2021). "Collectively, it is hoped, IL‐25 might be a promising target in cancer treatment." (PMID 34128588, 2021). "Thus, in this study, we aimed to discuss the multifarious role of IL‐25 in cancer development." (PMID 34128588, 2021). "Using IL‐25‐based therapies might introduce novel approaches in cancer treatment." (PMID 34128588, 2021). "In future study, the role of IL-25 in activating antigen-presenting cells may warrant evaluation, especially for revealing and developing the pharmacological basis of IL-25-mediated anti-metastatic activity and the development of cell-based cancer vaccines." (PMID 27089063, 2016). "IL25 inhibited phosphorylation of AMPK and promoted GLI1 accumulation to maintain cancer stem cells." (PMID 35359953, 2022). "The levels of IL-25 in serum and tissue were significantly increased in HCC patients (n = 10) as compared to non-cancer patients (HH) (n = 5)." (PMID 31296243, 2019). "Currently, there are no clinical trials related to IL-33 or IL-25 for cancer treatment." (PMID 37455828, 2023). "Our previous study showed that IL25 was not directly affecting the growth, apoptosis, or migration in HCC, but promoted macrophages secret CXCL10 and led to cancer metastasis." (PMID 35359953, 2022).
inflammation (28 papers, 2012 to 2023). Aberrant reaction of the microcirculation characterized by movement of fluid and leukocytes from the blood into extravascular tissues. "In various models of airway inflammation in mice, IL-33, IL-25 and/or TSLP showed increased expression in the lungs after inhalation of antigens." (PMID 33723298, 2021). "The result showed that PM exposure resulted in the pulmonary accumulation of IL-33 and IL-25 in the HDM-induced airway inflammation (p < 0.001, p < 0.01)." (PMID 34254951, 2021). "These epithelial cytokines are believed to play important roles in mediating immune response in lung, and intranasal treatment of mice with IL-33 or IL-25, has been shown to induce pulmonary inflammation." (PMID 34970267, 2021). "In a mouse model of house dust mite-induced airway inflammation, IL-25 was shown to promote Th2 and Th9 inflammation in lungs by targeting DCs." (PMID 30519393, 2018). "IL-17rb-/- and IL-17ra-/- mice fail to respond to IL-25, and both knockout strains are refractory to pulmonary inflammation induced by intranasal application of IL-25." (PMID 28771607, 2017). "In this study, to identify the detailed role of IL-25 in promoting innate immune responses in asthmatic airway inflammation, the expression levels of ICOS and T1/ST2 on nuocytes were detected by means of flow cytometry." (PMID 27617447, 2016). "Interestingly, inhibition of glycolysis significantly decreased inflammatory cytokine levels (IL-25 and IL-33), suggesting glycolysis to be involved in asthmatic lung inflammation." (PMID 36441389, 2023). "Interestingly, IL-25 expression was also decreased in the lungs from the mouse model of neutrophilia-dominant airway inflammation." (PMID 37898756, 2023). "Whereas interleukin-25, which is proven to be deficiently synthesized in IBD patients, seems to have beneficial effects and inhibits the tissue-damaging immune response in gut inflammation." (PMID 35160321, 2022). "It has been shown that during gut inflammation the production of IL25 protein is diminished." (PMID 34359123, 2021). "Th2-lymphocyte factor-induced inflammation disease can be regulated by IL-25 and Tslp which promote the initiation of Th2 inflammation in airway mucosa, through facilitating Th2-cell proliferation and differentiation as well as activating group 2 innate lymphoid cells." (PMID 34630778, 2021). "On the contrary, Ncf1 appeared to play only a minor role in IL-25 stimulated lung inflammation." (PMID 34970267, 2021). "Increased expressions of IL-17RB and ST2 on mDCs are associated with enhanced local Th2 inflammation in NP, suggesting that mDCs might play a role in IL-25- and IL-33-induced type 2 responses and eosinophilic inflammation in NP." (PMID 30519393, 2018). "Therefore, the positive correlation among IL-25, IL-5 and IL-13 indicates that IL-25 plays a role in the increase of Th2-type cytokines (IL-5 and IL-13) that induces asthmatic airway inflammation and promotes Th2-type adaptive immune responses." (PMID 27617447, 2016). "Since long-term exposure of mice to HDM, but not OVA, results in chronic airway inflammation associated with tissue remodeling, these observations suggest that IL-25, IL-33 and TSLP play different pathogenic roles in the acute and chronic phases of airway inflammation." (PMID 24205109, 2013). "Others showed that IL-25 was involved in tissue remodeling during HDM-induced airway inflammation." (PMID 24205109, 2013). "Moreover, in a mouse model of lung inflammation, we have shown that blocking IL-25 with a neutralizing anti-IL-25 antibody completely abrogated airways hyperreactivity (AHR)." (PMID 22539101, 2012). "Furthermore, the IL-17RB and ST2 expressions on mDCs were also correlated with the IL-5 mRNA level and eosinophil numbers in NP tissues, suggesting that mDCs might play a role in IL-25- and IL-33-induced type 2 responses and eosinophilic inflammation in NP." (PMID 30519393, 2018).